DLK1 (delta like non-canonical Notch ligand 1)
Diseases named in the same sentence as DLK1 in open-access papers (continued):
Sharing a sentence is not in itself a finding about the gene and the disease.
teratoma (1 paper, 2015). A non-seminomatous germ cell tumor characterized by the presence of various tissues which correspond to the different germinal layers (endoderm, mesoderm, and ectoderm). "In the present study, we found that the Dlk1-Dio3 gene locus in hpESCs is aberrantly expressed and methylated, which correlated with teratoma formation." (PMID 25879223, 2015).
triple-negative breast carcinoma (1 paper, 2022). An invasive breast carcinoma which is negative for expression of estrogen receptor (ER), progesterone receptor (PR), and human epidermal growth factor receptor 2 (HER2). "In a previous work, we reported that different levels of DLK1 expression exerted a significant modulation on the growth and tumorigenic properties of MDA-MB-231 triple-negative breast cancer cell line." (PMID 35163478, 2022). "The effects on the growth and invasion capabilities of MDA-MB-231 cells observed upon the reconstitution of DLK1 or upon DLK2 overexpression, are consistent with the role of NOTCH signaling in the growth of triple-negative breast cancer cells." (PMID 35163478, 2022). "We estimate that this property is suitable for studying the potential effects of the forced overexpression of DLK2 on triple-negative breast cancer cell growth without interfering with the expression of its homolog, DLK1." (PMID 35163478, 2022).
urothelial carcinoma (1 paper, 2014). A malignant neoplasm derived from the transitional epithelium of the urinary tract (urinary bladder, ureter, urethra, or renal pelvis). "Our data support the idea that the main cause of the prevalent downregulation of DLK1 and MEG3 in urothelial carcinoma is epigenetic silencing across the 14q32 imprinted gene cluster, resulting in the unusual concomitant inactivation of oppositely expressed and imprinted genes." (PMID 25741387, 2014). "DLK1 mRNA was significantly reduced in urothelial cancer tissues compared to normal bladder tissue and was low or undetectable in all investigated urothelial carcinoma cell lines but remained detectable, albeit at lower levels, in cultured normal urothelial cells." (PMID 25741387, 2014). "Unexpectedly, we found that expression of both DLK1 and MEG3 was strongly diminished in urothelial carcinoma tissues and cell lines." (PMID 25741387, 2014). "The genes DLK1 and MEG3 within this cluster are tumor suppressor candidates in urothelial carcinoma due to their known functions in the regulation of cell growth and development." (PMID 25741387, 2014). "Thus, whereas copy numbers of the 14q region were variously increased or decreased in urothelial carcinoma tissues and cell lines, MEG3 and DLK1 expression was reduced in almost all urothelial cancer tissues and cell lines, irrespective of copy numbers." (PMID 25741387, 2014). "Unfortunately, neither these authors nor others have explicitly reported on DLK1 in urothelial carcinoma." (PMID 25741387, 2014). "In previous reports on other cancer types, either DLK1 or MEG3 was reported to become deregulated, but not both genes, as we observed in urothelial carcinoma." (PMID 25741387, 2014).
vitamin B12 deficiency (1 paper, 2024). A disease characterized by low serum levels of vitamin B12, either inherited or acquired. "In the present study, vitamin B12 deficiency reduced the expression of the Dlk1 gene regardless of the amount of folic acid available in the maternal placenta of the F0 generation." (PMID 39543691, 2024).
vitamin deficiency (1 paper, 2024). A disorder that is caused by the deficiency of a vitamin. "In addition, cells in both vitamin deficiency groups (BDFD) also showed a significant increase in the expression of the Dlk1 gene by 2.3-fold (p = 0.0189) upon treatment with 5-azacitidine compared to that in untreated cells in the same group." (PMID 39543691, 2024).
tumor (110 papers, 2005 to 2026). "Expression data from mice and human ACC indicate that DLK1 is associated with increased malignancy and tumor aggressiveness." (PMID 40035383, 2025). "For example, DLK1 was one of the most upregulated genes for all KO genotypes and was previously shown to be a tumor pericyte-associated antigene." (PMID 40478324, 2025). "Low levels of DLK1 expression accelerated tumor growth in vivo, whereas high levels of DLK1 expression caused tumors that grew more slowly than normal." (PMID 35163478, 2022). "We recently demonstrated that, similar to what was observed in the subventricular zone neural stem cell niche, tumor-associated astrocytes secrete high levels of DLK1, especially when they are activated by hypoxia." (PMID 34606325, 2022). "We found increased secretion of DLK1 from tumor-associated astrocytes subjected to stresses of the tumor microenvironment, such as hypoxia and ionizing radiation." (PMID 33142235, 2020). "The mechanisms underlying these effects on tumor cell behavior remain poorly understood, but likely include signaling from the extracellular, soluble domain of DLK1." (PMID 33142235, 2020). "We previously reported CAR and Wnt/β-catenin signaling–dependent transcriptional effects at the pluripotency-associated Dlk1-Dio3 imprinted gene cluster noncoding RNAs in the liver of mice treated with tumor-promoting doses of PB." (PMID 31615920, 2019). "Other than tumor histologic type, DLK1 nuclear expression was associated with cell differentiation (P=0.042) and tumor size (P=0.010)." (PMID 31661545, 2019). "DLK1, the tumor activator, was down‐regulated in the KMT2D mutation group while DRD5 was up‐regulated and acted in the opposite way; the expression change trends were validated by qRT‐PCR results." (PMID 30984543, 2019). "RTL1 is the key member of the Dlk1-Dio3 imprinted region, and the loss of imprinting in this region and network disorder of imprint regulation are closely related to tumour formation." (PMID 29285312, 2017). "DLK1 expression is associated with adverse clinical outcomes and is increasingly implicated in maintaining a de-differentiated, stem-like tumour phenotype that might contribute to tumour progression and therapeutic resistance." (PMID 42023826, 2026). "In summary, the target pathway enrichment analysis shows that DEMIRs on Dlk1-Dio3 GIR may affect hepatocarcinogenesis by regulating multiple tumor-associated metabolic pathways." (PMID 34135934, 2021). "We next tested whether there is an association between a higher AIFM3 and DLK1 copy number state and age of onset, gender, tumor size, multifocality, extrathyroidal extension, vascular invasion and AJCC staging system." (PMID 33435319, 2021). "The target pathway enrichment analysis revealed that DEMIRs encoded by Dlk1-Dio3 GIR might have a crucial role in driving hepatocarcinogenesis by regulating multiple tumor-associated metabolic pathways." (PMID 34135934, 2021). "Its expression is associated with tumor cell properties like migration, invasion, and stemness in cancer, however, many outstanding questions remain regarding the function and regulation of DLK1." (PMID 32205867, 2020). "•High levels of soluble DLK1 are associated with tumor aggressiveness and lethality." (PMID 33142235, 2020). "DLK1 has previously been associated with hypoxia in other tumor types, suggesting that DLK1 expression and activity may both be driven by hypoxia-dependent mechanisms." (PMID 32205867, 2020). "It is important to note that DLK1 expression is not limited to tumor-associated astrocytes, and soluble DLK1 may be derived both from other stromal cell types and tumor cells themselves." (PMID 33142235, 2020). "We evaluated that whether DLK1 and NCOR1 co-expression in nucleus is associated with any tumor character, the answer of which might give a hint on the mechanism of how DLK1 affects Notch signaling pathway." (PMID 31661545, 2019).
tumor (continued). "A previous study in this lab has revealed that DLK1 is associated with tumor invasion, although the mechanism is still unknown." (PMID 24621612, 2014). "Considering that Dlk1 appears to be consistently associated with the muscle-derived neoplasias combined with our previous demonstration of expression in human, fetal muscle and in myopathies, we next wondered how Dlk1 influences immature myogenic cells and myogenesis." (PMID 23577150, 2013). "Additionally, a link was established between down-regulation of the expression of miRNAs encoded in the Dlk1 – Gtl2 cluster and higher tumor proliferation leading to shorter patient survival times." (PMID 20161787, 2010). "As we had observed gene expression changes in Snail overexpressing tumors indicative of an inflammatory tumor microenvironment, we considered the possibility that the Snail-mediated induction of inflammatory cytokines could cause the Dlk1-Dio3 locus repression in immune cells." (PMID 30190790, 2018). "A recent study on CRC immunotherapy developed an αDC1 vaccine targeting the tumor pericyte antigen DLK1." (PMID 41320679, 2025). "We next assessed for tumor expression of DLK1 using RNA-seq data from a cohort of ~1000 adult patients with treatment refractory metastatic cancers." (PMID 40595495, 2025). "The DC1 vaccine against the tumour pericyte antigen DLK1 demonstrated significant anti-tumour effects in a homozygous mouse model, providing a new strategy for immunotherapy of CRC." (PMID 41320679, 2025). "Here the authors report that the Notch ligand DLK1 is highly expressed in ACC acting as a regulator of tumor cell plasticity and chemoresistance, and that DLK1 can be targeted with an antibody drug conjugate." (PMID 40595495, 2025). "Immunohistochemistry assays provided further confirmation of the high expression of DLK1 and RCN1 in tumour tissues, suggesting that they were associated with tumour progression." (PMID 39548559, 2024). "This works identifies DLK1 as a novel immunotherapeutic target that regulates tumor cell plasticity and chemoresistance in ACC." (PMID 39416174, 2024). "We next assessed tumor expression of DLK1 using RNA-seq data from a cohort of ~1000 adult patients with treatment refractory metastatic cancers." (PMID 39416174, 2024). "Validation analysis showed that DLK1 gain is correlated with increased protein expression, larger tumor size and advanced tumor stage (III and IV)." (PMID 39595993, 2024). "DLK1-expressing tumor cells have a higher proliferation rate, higher invasive capacity with epithelial mesenchymal transition, and resistance to treatment compared with cancer cells not expressing DLK1." (PMID 39769389, 2024). "We next investigated the anti-tumor activity of ADCT-701 among three DLK1+ ACC PDX models: 164165, 592788, and POBNCI_ACC004." (PMID 39416174, 2024). "By conducting a differential analysis based on the transcriptional expression patterns of the CNVhigh and CNVlow regions, we further identified crucial genes related to tumour progression, such as DLK1 and RCN1." (PMID 39548559, 2024). "Consistently, IHC analysis at early timepoints (days 6 and 9) identified a significantly higher Dlk1+ fraction of hepatocytes in the tumour-prone PGK-NRASG12V or UBC-NRASG12V mice than in CAGGS-NRASG12V mice." (PMID 39112713, 2024). "We have also previously documented by IF that DLK1 is expressed by pericytes in the MC38 tumor microenvironment (TME)." (PMID 37849752, 2023). "We observed overall reduction in expression of Cyp2e1 in tumor tissues in comparison with normal livers but marked induction of Igf2, Afp, Dlk1, Epcam and Gpc3 in tumor areas." (PMID 37414763, 2023). "The functional relevance of CNA was also assessed by in silico analysis, and CNA status was found to be correlated with protein expression (DLK1, p = 0.01), tumour size (DLK1, p = 0.04), and tumour staging (AIFM3, p = 0.01 and DLK1, p = 0.05)." (PMID 37835559, 2023).
tumor (continued). "Yet, directing αDC1 vaccines against endogenous DLK1 on tumor-derived stromal cells was beneficial to mice only in combination with anti-PD-1 blockade." (PMID 37849752, 2023). "In mice xenograft models, DLK1 overexpression exerted its effects by increasing proliferation and neovascularization of the tumors, leading to increased tumor volume." (PMID 38269089, 2023). "Here, we demonstrate the pre-clinical ability of an αDC1 vaccine to target the tumor-derived pericyte marker delta-like 1 homologue (DLK1) to achieve improved resolution of disease." (PMID 37849752, 2023). "Many of these (DLK1, GAB2, BOLA2B, AOX1 and AGER) were closely related to cell proliferation and tumor progression, and associated with poor prognosis in HCC." (PMID 35331184, 2022). "In the RCC study, the DLK1 vaccine in murine models results in the inhibition of RCC growth, but also in the compensatory expression of DLK2 by tumor-associated pericytes." (PMID 35456435, 2022). "They showed that DLK1 silencing reduced tumor growth in an orthotropic xenograft as well as in a chemical DEN-HCC induced model due to a G1 phase arrest." (PMID 35805898, 2022). "In conclusion, DLK1 plays an important role in the regulation of stem cell pools both in tissue differentiation during development and in different neoplasia." (PMID 34606325, 2022). "Progress in recent years suggest differential functions of extracellular, soluble DLK1 as a paracrine stem cell niche-secreted factor, and has revealed a role for the intracellular domain of DLK1 in cell signaling and tumor stemness." (PMID 34606325, 2022). "It has been reported that delta-like 1 homologue (DLK1) participates in the tumor microenvironmental remodeling of ccRCC, but the relationship between delta-like 2 homologue (DLK2, a DLK1 homologue) and ccRCC is still unclear." (PMID 35456435, 2022). "The analysis of patient tumor samples revealed evidence of Wnt and β-catenin activation, as well as upregulation of several imprinted genes such as DLK1 and MEG3." (PMID 35805898, 2022). "A change in the level of DLK1 expression was also observed in tumor cells, and the gene was more actively expressed in HB cells than in HCC." (PMID 34884942, 2021). "Vascularisation is an important component of tumor growth and a target for therapy; the NOTCH antagonist delta-like 1 homologue (DLK1) was previously identified as a tumor pericyte-associated antigen in various carcinomas, also in renal cell carcinomas." (PMID 34957538, 2021). "CNA status correlated with protein expression (DLK1, p = 0.01), tumor size (DLK1, p = 0.04) and AJCC staging (AIFM3p = 0.01 and DLK1p = 0.05)." (PMID 33435319, 2021). "Tumor cells show interaction with the microenvironment, including endothelial cells through DLK1 and BMP signaling, as well as tumor interactions with hepatic stellate cells as well as endothelial cells." (PMID 34497364, 2021). "Enhanced DLK1 levels in PDGFB + DLK-A tumors were confirmed by co-staining with the tumor marker Olig2." (PMID 32205867, 2020). "The stem gene DLK1 is overexpressed in mice that overexpress P62, and tumor formation is more aggressive due to cancer stemness." (PMID 32391379, 2020). "We found that astrocytes, when exposed to stresses of the tumor microenvironment such as hypoxia or ionizing radiation, increased secretion of soluble DLK1." (PMID 33142235, 2020). "Among the downregulated ABC genes, DLK1 has been shown in many recent studies to function as a tumor suppressor." (PMID 32539762, 2020). "The band pattern was more complex in tumor samples compared with controls, indicating tumor-specific DLK1 regulation." (PMID 32205867, 2020). "Another program was exclusively found in one ST-RELA tumor, MUV043, and was associated with connective tissue development and extracellular matrix organization (e.g., DLK1, PCP4, ACPT) (ST-RELA-variable)." (PMID 32663469, 2020). "In vivo, however, we detected DLK1 in the nucleus not only in hypoxic tumor areas, but also in the perivascular niche." (PMID 32205867, 2020).
tumor (continued). "DLK1 nuclear expression was inclined to appear in well differentiated or smaller (less than 5 cm in diameter) tumor sample." (PMID 31661545, 2019). "Surprisingly, we uncovered two signaling pathways leading to tumor suppression in the mutation group, FOX1–miR‐1224‐5p–DLK1 and HIF/GATA5–miR‐133a‐3p–DRD5." (PMID 30984543, 2019). "Immunofluorescence was performed for intuitively characterizing nuclear translocation of DLK1 in tumor cells." (PMID 31661545, 2019). "We summarized the distribution of DLK1 positive staining in either cell nuclear or cytoplasm, as well as the tumor histological type." (PMID 31661545, 2019). "In SCC, the overexpression of DLK1 was correlated with tumor stage (P=0.008), node metastasis (P=0.007) and differentiation (P=0.007)." (PMID 31661545, 2019). "We investigated the correlation of DLK1 expression and the clinical feature of the patients, including patients’ age, gender, tumor stage, tumor size, node metastasis status and cell differentiation degree." (PMID 31661545, 2019). "Apart from its roles in regulating cell differentiation, such as osteogenesis and adipogenesis, DLK1 had been shown to contribute to tumor cell invasion and is a negative regulator of Notch signaling." (PMID 31185898, 2019). "The nuclear localized DLK1 was observed in 107 of 351 non-small cell lung cancer (NSCLC) samples and was associated with tissue differentiation and tumor size." (PMID 31661545, 2019). "Several lines of evidence suggest that increased methylation of the MEG3 ICR, regulating a known tumor suppressor, is associated with decreased expression of MEG3, albeit with increased expression of the reciprocally imprinted DLK1 gene." (PMID 30246009, 2018). "While an increasing body of literature contributes to our understanding of the Dlk1-Dio3 locus in cancer cells, its role in tumor-infiltrating immune cells remains elusive and reports on its functions in immune cells in general are sparse." (PMID 30190790, 2018). "The Dlk1-Dio3 locus repression mediated by Snail was found to occur specifically in several populations of tumor-infiltrating immune cells." (PMID 30190790, 2018). "Intriguingly, Snail mediates the Dlk1-Dio3 locus repression specifically in tumor-infiltrating immune cells in a paracrine fashion via the secretion of a soluble factor by epithelial tumor cells." (PMID 30190790, 2018). "Our results thus indicate that the Snail mediated Dlk1-Dio3 locus repression rather occurs in the tumor-infiltrating immune cells than in the tumor epithelial cells." (PMID 30190790, 2018). "Because RTL1 is the only consistently altered gene detected in all SB-induced tumours with Dlk1-Dio3 integrations, it has been suggested that RTL1 activation is a driver of liver cancer." (PMID 29285312, 2017). "Observed during 21 to 42 days post inoculation, the xenograft HCCs with the inducible DLK1 knockdown exhibited a significant reduction of tumor volume and weight, as compared to the controls with luciferase knockdown." (PMID 27683116, 2016). "Our data also demonstrates significant up-regulation of COL11A1, COL10A1, MMP1 and MMP13, and significant down-regulation of COL6A6 and DLK1 in tumor relative to non-tumor adjacent breast tissue." (PMID 27857161, 2016). "In the DEN-induced mouse HCC model, the adenoviral-mediated Dlk1 knockdown also reduces tumor growth of mouse HCCs." (PMID 27683116, 2016). "We also further evaluated the effect of DLK1 knockdown on spheroid formation of HCC cells due to DLK1 as potential biomarker of tumor stem/progenitor cells of HCCs." (PMID 27683116, 2016). "In the human HCC xenograft tumor models, including subcutaneous and orthotopic tumor xenografts, DLK1 knockdown can significantly suppress tumor growth." (PMID 27683116, 2016).